CTSL (cathepsin L)
Diseases named in the same sentence as CTSL in open-access papers (continued):
Sharing a sentence is not in itself a finding about the gene and the disease.
cancer (continued). "The usage of isoform CTSL-002 was very high in all cancers; the other five isoforms were found to be minimally expressed." (PMID 35414771, 2022). "Further analysis of the expression of CTSL mutant showed a correlation with FURIN and TMPRSS2, suggesting a potential role of CTSL mutations in modulating SARS-CoV-2 entry in cancers." (PMID 35414771, 2022). "and reported them as promising candidates for cancer therapeutics due to their cathepsin L inhibition activity." (PMID 35388095, 2022). "Our study highlights the value of targeting CTSL as a therapeutic strategy to combat cancer and COVID-19 pandemic." (PMID 35414771, 2022). "In summary, histone density associates with specific proteome signatures across cancer cell lines, and is linked to the expression of chromatin components, mitochondrial proteins, and known histone regulators (HMGB1, CTSL)." (PMID 36030322, 2022). "This study evaluated the inhibitory activity of SnuCalCpIs against cathepsin L, which plays a crucial role in cancer cell migration through ECM degradation." (PMID 35388095, 2022). "Although not directly demonstrated for HCC, studies using other types of cancer demonstrated a role for both CTSL and CTSD in angiogenesis." (PMID 36289617, 2022). "The upregulation of HDAC and CTSL enzymes in cancer has previously been exploited in a prodrug strategy whereby an ε-acetylated lysine linkage was selectively cleaved to release an active drug in a stepwise manner." (PMID 34371769, 2021). "Taken together, these results demonstrate that TFEB-induced ITGB1 degradation can restrain the mobility of cancer cells in part via the CTSL mediated lysosomal degradation." (PMID 33803301, 2021). "In our analysis, elevation of ACE2, TMPRSS2, and CTSL in cancer vs. normal tissue was observed in many of the tissues examined, including many non-respiratory tract tissues." (PMID 33633121, 2021). "Together, from these two datasets, it appears that ACE2/TMPRSS2 have transient elevation with cancer treatments that resolve in less than 20 days post-treatment, while CTSL exhibits a prolonged elevation at for at least 4–6 weeks post-treatment." (PMID 33633121, 2021). "Of note, many of the top ranked normal tissues for CTSL expression were among the bottom-ranked malignant tissues for CTSL expression, and vice versa with cancer type having a large effect on CTSL tissue expression rank." (PMID 33633121, 2021). "CTSL is highly expressed in many cancers, degrades extracellular matrix (ECM) proteins, and promotes cancer cell invasion and metastases." (PMID 34209658, 2021). "More importantly, we demonstrate that EpCAM cancer-associated mutations alter EpCAM cellular function and localization, abrogate the ability of EpCAM to inhibit CTSL activity, and impact CTSL-driven cancer cell invasion." (PMID 33980181, 2021). "The common TMPRSS2 and FURIN associated genes CTSL, MYC, AKT1, and SRC displayed positive correlations with their corresponding subjects except for the FURIN and MYC correlation in cancers (R 0.012; p 0.199)." (PMID 33796097, 2021). "In an extended panel of human cancer cell lines, EpCAM expression is inversely correlated with CTSL activity." (PMID 33980181, 2021). "While many cancers demonstrate overexpression of CTSL, it is unclear if this directly corresponds to increased CTSL and metastatic activity." (PMID 33980181, 2021). "A recent study reported that COVID-19 infection of host cells is facilitated by transmembrane protease serine 2 (TMPRSS2), angiotensin-converting enzyme 2, and other host cell proteases, such as cathepsin L, which is highly expressed in cancer patients." (PMID 33628602, 2021). "In CTSL, its high expression was involved in several cancer pathways, such as JAK signaling pathway and cancer signaling pathway." (PMID 34168974, 2021).
cancer (continued). "Mechanistically, platyphyllenone reduced p38 phosphorylation, decreased β-catenin and Slug, increased E-cadherin expression, and reduced cathepsin L expression, which collectively led to a reduction in cancer cell migration and invasion." (PMID 34065077, 2021). "CTSL is a powerful lysosomal cysteine proteinase, and CTSL expression and activity is markedly increased in advanced cancers." (PMID 33980181, 2021). "Appropriate cell lines were selected on the basis of mRNA levels of HDAC I class and CTSL using Cancer Cell Line Encyclopedia RNA sequencing database." (PMID 34371769, 2021). "Gonzalo’s lab demonstrated that 1,25(OH)2D stabilized TP53BP1 via its interaction with VDR and promoted DSBR through the inhibition of CTSL, which is important in cancer progression and is involved in TP53BP1 degradation." (PMID 32456160, 2020). "Essentially, this notion is limited to findings showing that cathepsin B and legumain can be found in the nucleus of cancer cells and there is also data showing that cathepsin L can be localized in the nucleus of embryonic stem cells." (PMID 32709152, 2020). "It has been noted that in cancer cells, cathepsin L is induced by MYC; moreover, cathepsin C is known to be up-regulated by MYC in TAMs." (PMID 33081056, 2020). "Accumulating evidences reveal that CTSL specifically high-expressed in a wide range of human cancers." (PMID 30732622, 2019). "On the other hand, cathepsin L-mediated cancer progression was largely due to its secretion from cancer cells, whereas the effect of cathepsin X was due to its release from both sources." (PMID 30897858, 2019). "Cathepsin L (CTSL) is a cysteine protease known to have important roles in regulating cancer cellular resistance to chemotherapy." (PMID 31370861, 2019). "Increased and more persistent inhibition of cathepsin L in treated cancer cells was observed following AFt-encapsulation of Neq0554, consistent with cellular retention and sustained release of Neq0554 in acidic cytosolic compartments." (PMID 35539052, 2019). "In both cancer cell lines, total cathepsin L activity was more effectively inhibited following exposure to AFt-encapsulated agent, compared to naked Neq0554." (PMID 35539052, 2019). "Our lab has previously delineated the role of transcriptional as well as post-transcriptional up-regulation of CTSL expression in several cancers." (PMID 31824841, 2019). "Cathepsin L (CTSL), a cysteine protease that belongs to the papain-like family, has been found to be overexpressed in several types of human carcinomas arising from the lung, ovary, cervix, breast and colon." (PMID 31370861, 2019). "Given that this probe does not react with other cathepsins, it has the potential to facilitate the understanding of cathepsin L function and provide new information about the biological framework of cathepsin L-dependent or -related cancer progression." (PMID 29719685, 2018). "The MP-cL3 probe selectivity for cathepsin L over cathepsin B is of special importance, as cathepsin B is overexpressed in many types of cancers and masks cathepsin L proteolytic activity, making its analysis more complex." (PMID 29719685, 2018). "Cathepsin L of cancer cells has been shown to play an important role in degradation of extracellular matrix for metastasis." (PMID 29560748, 2018). "In summary, we have developed the first selective cathepsin L ABP, which allows accurate detection of cathepsin L activity in cancer cells." (PMID 29719685, 2018). "Cathepsin L is considerably overexpressed in a wide variety of cancers and promotes tumor growth, migration, invasion, angiogenesis, and metastasis." (PMID 27754413, 2016). "In the MMTV-PyMT mouse model overexpression of human Cathepsin B and Cathepsin L promoted migration and invasion of cancer cells as well as metastasis formation." (PMID 27542270, 2016).
cancer (continued). "There are substantial clinical and cell biological data linking cysteine cathepsins, foremost cathepsin B (Ctsb) and cathepsin L (Ctsl), to cancer progression and metastasis." (PMID 25744631, 2015). "On the other hand, a series of benzophenone TSC analogs have been developed as cathepsin L inhibitors with a potential application as therapeutic agents against cancer metastasis." (PMID 26360247, 2015). "The first observed function of CTSL in cancer progression was its ability to promote cancer metastasis." (PMID 25384089, 2014). "Activity prediction using 3D QSAR model further validated their potential as worthy drug candidates against cathepsin L for treatment of cancer." (PMID 24564425, 2013). "A further cathepsin L structure-based screen identified two top scoring compounds as potent anti-cancer leads." (PMID 24564425, 2013). "Results of this study will also guide the design of potent anti-tumorals based on cathepsin L inhibition to further strengthen already available drug batch against cancer." (PMID 24564425, 2013). "However, its CtsL-mediated degradation allows cancer cells to avoid cell growth arrest and reduce cell death in response to DNA damage." (PMID 39851495, 2025). "Another cathepsin enzyme, cathepsin L, is upregulated in various human cancers." (PMID 38611849, 2024). "Cathepsin L (CTSL) expression is dysregulated in a variety of cancers." (PMID 38139037, 2023). "Additionally, due to the lack of experimental evidence and mechanistic investigations, it is challenging to understand the relationship between SARS-CoV-2 and cancer data and the potential contribution of CTSL." (PMID 37292206, 2023). "It is possible that CTSL plays a key role in cancer progression and SARS-CoV-2 infection." (PMID 37292206, 2023). "Various types of cathepsin L inhibitors have been investigated as cancer cures." (PMID 35388095, 2022). "Therefore, it is critical to predict the susceptibility of cancer patients for SARS-CoV-2 and evaluate the correlation between disease outcomes and the expression of CTSL in malignant cancer tissues." (PMID 35414771, 2022). "The inverse correlation between cathepsin L levels and histone density raises the possibility that its expression may influence histone turnover in cancer cells through cleavage." (PMID 36030322, 2022). "Furthermore, CD or m62A inhibited CTSL expression in the cancer cell lines A549, MDA-MB-231, and/or PC3 in a dose dependent manner." (PMID 35414771, 2022). "CTSL expression was high in normal tissues and was increased in multiple cancer types." (PMID 35414771, 2022). "The prognostic value of CTSB and CTSL was further explored in pan-cancers." (PMID 35155389, 2022). "Significantly, CTSL has important roles in regulating cancer chemoresistance." (PMID 36133820, 2022). "Research has shown that increased levels of cathepsin L are correlated with decreased heart function in dilated cardiomyopathy, increased inflammation in rheumatoid arthritis, and increased malignancy of certain cancers." (PMID 41541591, 2022). "CTSL plays a key role in the formation, growth, invasion and migration of malignant tumors." (PMID 36133820, 2022). "Accordingly, inhibition of CTSL is shown to disrupt cell proliferation in cancer cells." (PMID 34905652, 2022). "Further studies are required to firmly establish how platyphyllenone-mediated reduction in cathepsin L expression may affect the epithelial to mesenchymal transition and control cancer metastasis." (PMID 34065077, 2021). "Through surveying CCLE (cancer cell line encyclopedia) expression profiles, we observed remarkably higher mRNA expression levels of both CTSL and FURIN in H2126, potentially indicating TMPRSS2-independent SARS-CoV-2 infection and explaining less efficacy of camostat mesylate in these cells." (PMID 33558541, 2021).
cancer (continued). "Together, our findings suggest that soluble/secreted EpCAM can suppress extracellular CTSL protease activity via its TY-1 domain, while cancer-associated EpCAM mutants that are not expressed on the cell surface do not retain this function." (PMID 33980181, 2021). "We also tested the ability of cancer cell lines transduced with EpCAM to inhibit CTSL." (PMID 33980181, 2021). "Preclinical studies have demonstrated that CTSL targeting in cancer patients may be an effective therapeutic strategy." (PMID 34209658, 2021). "Increasing evidences indicate that CTSL is highly specifically expressed in various cancers." (PMID 33860055, 2021). "It has been reported that secreted cathepsin B, cathepsin L and cathepsin S could cleave the cell adhesion molecule E-cadherin, promoting cancer cell invasion into the surrounding tissue." (PMID 33081056, 2020). "Moreover, CTSL can contribute to surface characteristics of cancer cells, which can be important in distinguishing cancer cells from their normal counterparts." (PMID 32456160, 2020). "Cathepsin L is overexpressed in cancer cells and could provide a specific target for delivery of anticancer agents." (PMID 35539052, 2019). "Moreover, CTSL transported into the nucleus plays an important role in regulating cellular transcription factors, and thus affects the morphology or activity of cancer cells." (PMID 30732622, 2019). "As a member of the early gene family, Egr-1 has an important role in drug resistance in cancer cells and could regulate the expression of CTSL." (PMID 31370861, 2019). "Specific inhibition of cathepsin L seems to be a general problem if cancer cells are used; a strong inhibitory effect on cancer cell proliferation was reported also for other specific chemical inhibitors and neutralizing antibodies of cathepsin L." (PMID 27031696, 2016). "Therefore, inhibition of cathepsin L by the SEP domain can be considered a promising target for cancer therapy." (PMID 27754413, 2016). "Targeting CTSL alters the behavior of drug-resistant cancer cells." (PMID 27351223, 2016). "In addition, pharmacological targeting of cathepsin L has proven to be of viable therapeutic benefit for the treatment of cancer." (PMID 27754413, 2016). "Cathepsin L localization, as well as the cell type of origin, may significantly alter the range of cathepsin L substrates and their contribution to cancer progression." (PMID 25927437, 2015). "The status of CTSL protein in carcinoma tissues is much higher than that in paracarcinoma tissues." (PMID 25384089, 2014). "Additionally, cathepsin L contributes to a variety of pathological processes, such as cancer and neurodegeneration." (PMID 24073275, 2013). "Differences exist, however, for the roles of cathepsin L in different cancer cell types." (PMID 17488522, 2007). "Furthermore, cathepsins including cathepsin L, when overexpressed, can be secreted and play a role in shaping the microenvironment in physiological and pathological processes, e.g., cancer and various inflammatory disease including those with autoimmune components." (PMID 32635226, 2020). "Importantly, only CTSL located in the nucleus could play an important role in regulating cellular transcription factors and thus affecting the progression of cancers." (PMID 30732622, 2019). "Thus, CTSL may represent a novel therapeutic target for reinforcing the efficacy of cancer chemotherapy." (PMID 31370861, 2019). "Recent work has demonstrated that CTSL may also regulate cancer cell resistance to chemotherapy." (PMID 27351223, 2016). "Hence, cathepsin L is expressed and activated in the cancer cells of Myc-driven PNETs in vivo." (PMID 25927437, 2015). "In addition, Cathepsin-L, Gabarapl1 and Bnip3, which are known gene targets of FoxO in skeletal muscle involved in protein degradation through the lysosomal/autophagy pathway, were also identified as FoxO targets during cancer." (PMID 25539728, 2014).
cancer (continued). "The broad expression of CTSB and CTSL in other tissues and cell types aligns with their general role in proteolytic pathways, but their co-expression with NRP1 in macrophages hints at a cancer-specific regulatory network." (PMID 40134439, 2025). "For example, CtsB, CtsL, and CtsS have been shown to extracellularly target the extracellular domain of E-cadherin and other adhesion molecules, thus contributing to EMT in cancer cells." (PMID 39851495, 2025). "Recent studies have revealed the role of several cathepsins in promoting or inhibiting various cancers (e.g., lung, ovarian, thyroid, and colorectal), including cathepsin B (CTSB), cathepsin L (CTSL), cathepsin G (CTSG), and cathepsin S (CTSS)." (PMID 38883596, 2024). "It has been established that cancerous tissues express Cathepsin L (CTSL), a proteinase that regulates cancer progression and SARS-CoV-2 entry." (PMID 37292206, 2023). "Subsequently, we will discuss the function of the most studied cathepsins (CTSB, CTSD, CTSL, and cathepsin (CTS)S) in NASH, followed by a description of the mechanisms of cathepsins in HCC by means of the renowned “hallmarks of cancer”." (PMID 36289617, 2022). "However, the impact of CTSL expression in SARS-CoV-2 infected cancer patients is still unknown." (PMID 35414771, 2022). "CD and m62A are nucleoside derivatives that have been reported to inhibit the expression of CTSL, another SARS-CoV-2 receptor, in cancer cell lines." (PMID 36177004, 2022). "KEGG analysis identified adhesion, hematopoiesis and cancer-related proteoglycans as affected pathways (e.g. metformin: CD9, CTSL, IL5, HGF; insulin: EGF, EZR, PLCG2, TFRC)." (PMID 33690729, 2021). "Various types of cancer cells increase production of proteases upon increase in acidity; these include MMP2, MMP9, CTSB (cathepsin-B), and CTSL (cathepsin-L)." (PMID 32079237, 2020). "The expression of cathepsin L is highly dysregulated in several human diseases, including diabetes, AAI, abdominal aortic aneurysm, liver fibrosis, and cancers." (PMID 32041276, 2020). "This strategy has thus enabled selective targeting of cancer cells, specifically with high HDAC and cathepsin L activities." (PMID 32041276, 2020). "CTSL is a key effector that induces EMT in various tumors, taking part in the regulation of invasion and metastasis of cancer cells and also modulating transcription of ERGs." (PMID 33340396, 2020). "CTSB, CTSL and CTSD were chosen due to their high expression, known function in bulk proteolysis and their reported functional importance such as cell growth and in diseases like cancer and neurodegeneration and neurodegeneration." (PMID 38775843, 2024). "In most cancers, the signature genes were differentially methylated compared to normal tissue; in particular, genes including as representatives NCOA4, CTSL, MCUB, ANXA5 and ANGPTL2 were usually hypermethylated, while genes including PDE2A and others were usually hypomethylated." (PMID 37660060, 2023). "Interestingly, for cancer cells, we found for the first time that HMGB1-mediated CTSL and autophagy-lysosome pathway by RNA-seq is strongly linked to the effects of naphplatin-mediated antitumor and anti-metastasis effects." (PMID 37537587, 2023). "We report that the mutant CTSL expression correlates with elevated FURIN expression in multiple cancers, while there is no such correlation in a few cancers (FURIN panel); but TMPRSS2 showed either increase or decrease in a few cancers (TMPRSS2 panel)." (PMID 35414771, 2022). "Cellular TFEB, through activation of autolysosome flux and induction of CTSL, could induce ITGB1 degradation, which consequently suppressed the cancer cell migration." (PMID 33803301, 2021). "Not surprisingly, cathepsin L inhibition by small molecule is considered a viable strategy for the development of novel anti-cancer agents." (PMID 32041276, 2020).